CXCL8 (C-X-C motif chemokine ligand 8)
Diseases named in the same sentence as CXCL8 in open-access papers (continued):
Sharing a sentence is not in itself a finding about the gene and the disease.
melanoma (continued). "For example, malignant melanomas express higher levels of CXCL1, CXCL2, and CXCL8 and receptors CXCR1, CXCR4, CCR10, and CCR7 compared with benign naevi." (PMID 34830780, 2021). "In the interleukin-4 and interleukin-13 signaling pathway, CXCL8 and MMP3 have published roles in melanoma growth and metastasis." (PMID 35008167, 2021). "Consistent with our data in fibroblasts, knockdown of p16 in the melanoma cells also decreased IL6 and CXCL8." (PMID 33550279, 2021). "The acquisition of an HIF1/NFkB-directed proinflammatory phenotype was characterized by the induced production and release of several factors, including TNFα, CCL5, IL6, VEGFA, CXCL8, PGE2 and CCL2, which had a prosurvival effect on melanoma cells." (PMID 32967672, 2020). "We observed that CXCL1 was predominantly produced by the melanoma cells, while IL6 and LIF were expressed mainly by the fibroblasts and CXCL8 by both cell types." (PMID 33182777, 2020). "It indicates that the expression of CXCL8 and CXCR2 contributes to the aggressive growth and metastasis of human malignant melanoma." (PMID 32894090, 2020). "Using primary melanocyte exosomes as control small extracellular vesicles, the authors detected inflammation-related melanoma exosome mRNA contents by RT-qPCR array, as well as upregulation of proangiogenic mediators (e.g., CXCL1, CXCL2, and CXCL8)." (PMID 33291683, 2020). "Consistent with mRNA expression, we found that the expression of CXCL8 and THBS1 protein in metastatic melanoma was significantly higher than that of primary melanoma, while the expression level of KIT was lower." (PMID 32894090, 2020). "Upregulation of CXCL1, CXCL2, and CXCL8 mRNA in A-375 and SKMEL-28 melanoma sEVs was the most consistent finding." (PMID 30870978, 2019). "Upregulation of pro-angiogenic chemokine ligand CXCL1, CXCL2, and CXCL8 mRNAs in A-375 and SKMEL-28 melanoma sEVs was the most consistent finding." (PMID 30870978, 2019). "Increased production of CXCL8 protein by A-375 and SKMEL-28 melanoma cells was the most consistent finding." (PMID 30870978, 2019). "In this study, we were able to correlate the expression of the most consistently upregulated A-375 and SKMEL-28 melanoma sEV mRNAs (CXCL1, CXCL2, and CXCL8) to CXCL1, CXCL2, and particularly CXCL8 protein production at the sEV source cell level." (PMID 30870978, 2019). "A vast majority of melanomas express CXCR2, which stimulates metastatic outgrowth, likely due to its ability to bind CXCL8." (PMID 30591657, 2018). "Previous studies had demonstrated that chemokine interleukin-8 (CXCL8), the ligand of CXCR2, acted as autocrine and/or paracrine growth and proangiogenic factor for melanoma through CXCR2, inducing invasion and migration." (PMID 29599927, 2018). "CXCL1 (melanoma growth-stimulatory activity/growth-regulatory protein α) and CXCL8 (IL-8) have important roles in inflammation, angiogenesis, tumorigenesis, and wound healing." (PMID 30631766, 2018). "In human melanoma xenografts, a BRAF inhibitor, with anti-proliferative and anti-metastatic properties, inhibited CXCL8 synthesis." (PMID 29977225, 2018). "Malignant melanoma expresses and secretes various CXC chemokines, including CXCL1, CXCL2, CXCL3 (GRO family chemokines) and CXCL8 (IL-8)." (PMID 28129639, 2017). "Presented here analysis demonstrated that melanoma cells secrete different levels CXCL1 and CXCL8 and rather high levels of CXCL2 and CXCL3 chemokines." (PMID 28129639, 2017). "The key chemokines involved in TAN recruitment to murine melanoma signal via the CXCR1 and CXCR2 axes, including CXCL1, CXCL2, CXCL6 and CXCL8." (PMID 28435677, 2017). "RT-PCR analysis showed that CXCL1 and CXCL8 were differently expressed in the analyzed cells with the overall lowest expression in WM164 and WM115 and the highest in WM873-1and in C8161 melanoma cells." (PMID 28129639, 2017).
melanoma (continued). "Limited number of reports on targeted inhibition of Gro family chemokines, CXCL8 (IL-8) and their receptors (CXCR1 and CXCR2) in various tumor models including melanomas, suggested a potential applicability of these approaches for tumor growth inhibition." (PMID 28129639, 2017). "CXCL8 or CXCR1/2-promoted angiogenesis has also been observed in numerous other cancer types, including melanoma, pancreatic, colon, and non-small cell lung cancer." (PMID 24276377, 2013). "Two high-affinity receptors for CXCL-8, CXCR1 and CXCR2, are differentially expressed on melanoma and endothelial cells." (PMID 23342280, 2012). "Compared with other chemokines, CXCL-8 (also called interleukin 8, or IL-8) of the CXC chemokine family deserves more attention as a player that regulates many cellular functions of melanoma." (PMID 23342280, 2012). "For example, CXCL1-3, CXCL-8, and CCL-5 have been reported to favor melanoma growth and/or progression." (PMID 23342280, 2012). "Melanoma cells have been shown to express the chemokine CXCL8, also known as interleukin-8 (IL-8), and a report has established that high serum levels of IL-8 are associated with tumor burden and poor prognosis." (PMID 22287956, 2012). "CXCL8 and CXCR2 were detected via immunostaining in metastatic lesions (e.g., draining LNs) in human malignant melanoma specimens, supporting their contributions to aggressive growth and metastasis." (PMID 24212647, 2011). "CXCL-8, a member of the CXC chemokine family, has been reported to induce migration, stimulate angiogenesis and promote tumour cell growth in melanoma and other malignancies." (PMID 19401689, 2009). "The chemokines CXCL1 (Gro-α) and CXCL8 (IL-8) are constitutively produced by melanoma cells and the corresponding receptors CXCR1 and CXCR2 are expressed on melanoma cells as well as on macrophages, neutrophils and eosinophils." (PMID 16052222, 2005). "ABX-IL8, functioning as a neutralizing antibody against CXCL8, can significantly inhibit the promoter activity and collagenase activity of MMP2 in melanoma cells, thereby diminishing tumor metastasis, reducing tumor angiogenesis, and augmenting tumor apoptosis." (PMID 39925807, 2025). "On the contrary, VM19 and VM25 cell lines, which were derived from primary melanomas, did not induce cytokine expression (except CXCL8 by VM25)." (PMID 39516494, 2024). "Finally, in a cohort of stage IV melanoma patients, we found increased circulating levels of neutrophil-related mediators, such as MMP-9, MPO, GM-CSF and CXCL8/IL-8, as well as increased levels of NET biomarkers, compared to healthy controls." (PMID 37525065, 2023). "Furthermore, IL-8/CXCL8 was shown to be a pro-inflammatory chemokine that plays an important role in a variety of human cancers, including melanoma, prostate, colon, breast and ovarian cancers, by mediating tumorigenesis and angiogenesis." (PMID 35211124, 2022). "CXCL8, CXCL9, CXCL10, CCL27, and C3AR1 have known immunomodulatory roles in melanoma." (PMID 35008167, 2021). "It has been recently demonstrated that IL-8 mediates invasion of melanoma cells and angiogenesis in a zebrafish model of melanoma, while downregulation of CXCL8 expression was sufficient to counteract the invasive capability of BCL-XLhigh melanoma cells." (PMID 32466509, 2020). "To conclude, CXCL8, THBS1 and KIT may be the hub genes in the metastasis of melanoma and thus may be regarded as therapeutic targets in the future." (PMID 32894090, 2020). "In this study, we highlighted the potential role of CXCL8, THBS1 and KIT in melanoma metastasis." (PMID 32894090, 2020). "Amelanotic C-32 melanoma cells produced less CXCL1, CXCL2, and CXCL8 than primary melanocytes." (PMID 30870978, 2019). "In addition, multiple clinical studies in medullary thyroid carcinoma, melanoma, breast, ovarian, and prostate cancer have shown a direct correlation between serum CXCL8/IL-8 levels and disease progression." (PMID 26379707, 2015).
melanoma (continued). "Our observations were increased tumor volumes in A375P-CXCL-8-injected mice, whereas tumor volumes in A375SM-anti-CXCL-8-injected mice were decreased, compared with controls, which confirmed the role of CXCL-8 in melanoma cell growth." (PMID 23342280, 2012). "Decreased production of VEGF and IL-8/CXCL8 upon treatment with RVT has already been described in various cell types, including fibroblasts, smooth muscle cells, epithelial cells, and melanoma-endothelial cell co-culture." (PMID 22451299, 2012). "In addition, our data demonstrated that the CXCL-8-induced and CXCR1- or CXCR2-dependent modulation of melanoma cell proliferation and migration was mediated through the ERK1/2 MAP kinase pathway." (PMID 19401689, 2009). "Furthermore, our study demonstrated that when the melanoma cells were incubated with an ERK1/2 inhibitor, CXCL-8-enhanced proliferation and migration was decreased." (PMID 19401689, 2009). "Immunohistochemical analyses of patient samples show an increased expression of CXCL8 and its receptors as melanomas transition from a radial (early stage) to vertical (later stage) growth phase, with CXCR1 upregulation being a key genetic difference between benign naevi and malignant melanoma." (PMID 34830780, 2021). "In addition, our study allows the identification of an immunosuppressive signature characterized by high GLI and low cytokine/chemokine expression (CCL7, CCL2, CCL20, CXCL8, CXCL1 and CXCL10), which could be used to stratify melanoma patients with poor survival." (PMID 39090759, 2024). "Though Nivolumab did not significantly alter serum cytokine profiles, in melanoma patients we observed a deviation from the physiological range for 7 out 18 cytokines tested: IL-1β, IL-6, CCL2, CXCL8, VEGF, IL-5 and IL-13." (PMID 35173725, 2022). "The expression of CXCL8 and CCND1 was significantly diminished in all melanoma cell lines, irrespective of their basal mRNA and protein levels that confirmed the inhibitory effect of 17-aminogeldanamycin on NF-κB activity." (PMID 32466509, 2020). "The influence of drugs on the expression of CCND1, CXCL8 and CTGF was also similar, when impact of drugs on the gene expression was compared between melanoma cells grown in SCM and the medium without growth factors for 2 days, 10 weeks and 3–4 months." (PMID 28829835, 2017). "Notably, type 2 cytokine responses (IL-5) and neutrophil responses (CXCL8/IL-8) were not altered by the changes of CD40 expression, suggesting that CD40 expression specifically correlates to the T-cell-dependent antitumor immunity in human melanoma tumors." (PMID 34092233, 2021).
asthma (465 papers, 2005 to 2026). "The CXCL8 gene (MIM 146930) encoding IL-8 is implicated in the etiology of several chronic inflammatory diseases, including asthma, rheumatoid arthritis, skin inflammation, periodontitis, and cancer." (PMID 40176809, 2025). "Neutrophils are now recognized to synthesize and secrete cytokines implicated in the severity of asthma exacerbations, namely CXCL8 (IL-8)." (PMID 38534377, 2024). "Sputum neutrophilia in asthma is strongly associated with increased production of several cytokines including IL-1β, IL-6, CXCL8, IL-12, IL-17A and TNF, and this correlates with bacterial burden, in particular Gamma-proteobacteria." (PMID 37180449, 2023). "IL-33, CXCL8, IL-17, C3a/C5a, IL-1β and LPS, associated with asthma pathophysiology, are important inducers of NET formation." (PMID 36359917, 2022). "Among these, LPS, IL-17, IL-33, CXCL8, C3a/C5a and IL-1β, which have been implicated in various aspects of asthma, are inducers of NET formation in neutrophils." (PMID 34342773, 2022). "We subsequently focused on IL-6, CXCL8 and GM-CSF as these cytokines are well-established to be up-regulated by PM exposure, as well as being implicated in the pathogenesis of asthma, with elevated concentrations seen in lungs of asthmatic individuals." (PMID 30157189, 2018). "The association between CXCL8 and reduced lung function, severity of asthma and airway hyper-responsiveness and allergic inflammation has been demonstrated in previous studies." (PMID 28558071, 2017). "In asthma, CXCL8 is a highly potent neutrophil chemoattractant causing neutrophil recruitment into the airways." (PMID 25713319, 2015). "Similarly, CXCL8, a well-studied proinflammatory chemokine, is linked to inflammation-driven diseases like asthma and inflammatory bowel disease through its dysregulated signaling." (PMID 40443529, 2025). "Severe asthma is associated with greater ASM mass with greater CXCL8 and eotaxin ASM expression." (PMID 37996952, 2023). "Interestingly, we found similar neutrophil responses between patients with suboptimally controlled asthma and well-controlled asthma, particularly with deficient fMLF induced CXCL8 and MMP-9 release." (PMID 26663987, 2015). "In asthma, both p300 and PCAF are associated with increased acetylation of histone H3, specifically at H3K18ac, at the CXCL8 gene promoter." (PMID 41008562, 2025). "Conversely, hypomethylation of proinflammatory genes, including iNOS, IL-13, and CXCL8, can promote their overexpression, further amplifying airway inflammation and asthma severity." (PMID 40806756, 2025). "This enhanced acetylation promotes CXCL8 gene expression, which is critical for the inflammatory response in asthma." (PMID 41008562, 2025). "Immunofluorescence staining indicated increased coexpression of STK33 and macrophage inflammatory protein 2 (murine homolog of IL-8/CXCL8) in the airway epithelial cells of mice with ovalbumin- and house dust mite–induced asthma." (PMID 41121245, 2025). "In contrast, non–T2 asthma shows basal cell hyperplasia, barrier impairment, and chromatin/methylation changes that favor neutrophil chemoattractant genes (e.g., CXCL8)." (PMID 40806756, 2025). "For instance, studies have evinced that rhinovirus infection in asthma patients leads to increased release of CXCL8/IL-8, while inhibition of CXCL8 expression can delay the exacerbation of asthma symptoms induced by viruses." (PMID 38640283, 2024). "The hub gene based on connectivity with other network members was CXCL8, a pro-inflammatory cytokine, which is linked to the diseases COPD, asthma, tuberculosis and lung cancer." (PMID 38242945, 2024). "Different cytokines were shown to play a key role in driving neutrophilic inflammation in asthma such as CXCL8, IL-17A or TNFα." (PMID 38892358, 2024). "Elevated CXCL8, neutrophil, and eosinophil levels are seen in the sputum and bronchial mucosa of asthma patients." (PMID 36725964, 2023).
asthma (continued). "In conclusion, this study demonstrates that, similar to human patients with asthma, horses with sEA have increases in CXCL-8, TNF-α, and IFN-γ compared to clinically healthy horses." (PMID 36713876, 2022). "It is able to also enhance production of neutrophil recruitment associated chemokines like CXCL8 (in humans), CXCL1, CXCL2, CXCL3, CXCL5, and IL-1b, particularly in mold allergen-induced asthma murine models." (PMID 35386663, 2022). "Thrombin is crucial in asthma severity as it can promote IL-8/CXCL8 production in lung epithelial cells, which is a potent chemoattractant for neutrophils." (PMID 36369000, 2022). "In this study, cytokine/chemokine concentrations in BALF revealed elevated TNF-α and CXCL-8 in sEA horses; therefore, these are potential targets for further subclassification and treatment in asthma." (PMID 36713876, 2022). "High amounts of neutrophils and the prototype CXCL chemokine, CXCL8, were detected in the tracheal aspirates of patients suffering from acute severe asthma, and these correlated positively with the severity." (PMID 36164329, 2022). "The cytokine suppresses the asthma-induced production of CXCL8, suggesting an inhibitory role for IL-38 in regulating allergic inflammatory responses." (PMID 35296330, 2022). "We confirmed that the patients with severe asthma exhibited higher amounts of IL-8/CXCL8 expression in their lung tissues, especially epithelial cells, than normal subjects or mild asthma patients." (PMID 36369000, 2022). "The pro-inflammatory mediators IL-6, TNF-α, and CXCL8 consequently entail the infiltration of activated immune cells, such as mast cells, DCs, and lymphocytes, which are involved in the pathogenesis of asthma." (PMID 35743888, 2022). "CXCL8 is overexpressed in airway secretions of severe asthma patients, and neutrophil airway infiltration is found in severe asthma." (PMID 34342773, 2022). "IL-38 acts as a partial antagonist receptor of IL-36 inflammatory cytokine, suppressing the asthma-induced production of CXCL8 and inhibiting allergic inflammatory responses." (PMID 35296330, 2022). "Other studies reconfirmed that elevated levels of C-X-C Motif Chemokine Ligand 8 (CXCL8) or IL-8 and neutrophil elastase are important biomarkers of Th2-low asthma." (PMID 35883681, 2022). "Plasma levels of several biomarkers of neutrophils activation such as MPO, MMP-9 and CXCL8 were increased in asthma patients compared to healthy subjects." (PMID 34342773, 2022). "Plasma concentrations of the neutrophil-derived mediators MPO, matrix metallopeptidase 9 (MMP-9) and CXCL8 were augmented in patients with asthma compared to healthy subjects, which suggests that PMNs are activated in vivo." (PMID 36359917, 2022). "In contrast, dexamethasone, a type of systemic corticosteroid commonly used in the treatment of asthma exacerbations, only partially inhibited the release of CXCL8." (PMID 32823491, 2020). "An additional study demonstrated decreased expression of miR-18a, -27a, -128 and -155 in HBECs derived from individuals with asthma, and further knockdown of these miRNAs led to increased expression of the proinflammatory cytokines IL-6 and CXCL8." (PMID 33255348, 2020). "TNFα induced a robust cytokine response in HBECs and so was chosen as the stimulus for primary bronchial epithelial cells; TNFα significantly increased secretion of IL-6 and CXCL8 from both healthy subjects and asthma patients (p < 0.05 for all comparisons)." (PMID 31974640, 2020). "CXCL8 is a crucial cytokine of the neutrophilic airway inflammatory process, which is also involved in virus-induced asthma exacerbation." (PMID 32823491, 2020). "Airway resistance is characteristic of asthma, in many clinic related studies, extracellular DNA, CXCL8, and neutrophils in BALF or induced sputum were negatively related to lung function and degree of symptom severity." (PMID 32756014, 2020).